RAC1 (Rac family small GTPase 1)
Diseases named in the same sentence as RAC1 in open-access papers (continued):
Sharing a sentence is not in itself a finding about the gene and the disease.
pancreatic cancer (continued). "Results in this report provide evidence supporting a novel function for Rac1 in the survival of pancreatic cancer cells after IR, which include the roles of Rac1 in the activation of G2/M checkpoint response and in the suppression of apoptosis induction following IR." (PMID 25344910, 2014). "Inhibition of Rac1 using specific inhibitor and dominant negative Rac1 mutant not only abrogates IR-induced G2 checkpoint activation, but also increases radiosensitivity of pancreatic cancer cells through induction of apoptosis." (PMID 25344910, 2014). "We also assessed the pancreatic cancer cells for changes in Rac1 level and activity following IR." (PMID 25344910, 2014). "Overexpression/hyperactivation of Rac1 GTPase is detected in the majority of pancreatic cancers." (PMID 25344910, 2014). "The data raises the possibility that the intrinsic radioresistance of pancreatic cancer cells might be a consequence of the constitutive activation of the Rac1 pathway in this disease." (PMID 25344910, 2014). "Rac1 and two of its GEFs, Tiam1 and Vav1, are overexpressed in more than 70% of pancreatic cancers." (PMID 25344910, 2014). "In the present report, we uncovered a similar role played by Rac1 in pancreatic cancer cells." (PMID 25344910, 2014). "Furthermore, it was demonstrated that the large GTPase Dynamin 2 potentiates invasive migration of pancreatic tumor cells through stabilization of the Rac1 GEF Vav1." (PMID 25313137, 2014). "The high Rac1 activity in the pancreatic cancer cells may make these cells more dependent on Rac1 for survival." (PMID 25344910, 2014). "Therefore, oncogenic K-ras activated Rac1 in Panc1 cells, and was probably responsible, at least in part, for the activation of Rac1 seen in the other pancreatic cancer cell lines with mutant K-ras genes." (PMID 24281169, 2010). "Since Tiam1 and Rac1 are active in the majority of pancreatic cancer cells, Tiam1 might mediate the activation of Rac1." (PMID 24281169, 2010). "Therefore, both depletion of Rac1 by RNA interference and pharmacological inhibition of Rac1 inhibited Mirk kinase activity in pancreatic cancer cells." (PMID 24281169, 2010). "Therefore, we stably expressed constitutively active EGFP (enhanced green fluorescent protein)-Rac1(V12) or dominant negative EGFP-Rac1(N17) in the pancreatic carcinoma cell line PANC-1." (PMID 19737400, 2009). "Second, expression of dominant negative Rac1(N17) results in increased amounts of E-cadherin as well as β-catenin in pancreatic carcinoma cells, which correlated with a stabilisation of E-cadherin/catenin adhesion complexes resulting in increased cell-cell adhesion." (PMID 19737400, 2009). "Whether SET increases Rac1 activity to increase migratory capabilities in pancreatic cancer remains unknown; however, it is likely that both SET overexpression and Rac1-induced SET recruitment to the cell surface can concomitantly amplify migratory signals during EMT." (PMID 28978088, 2017). "Furthermore, a switch from E-cadherin expression to P-cadherin, which is associated with a more invasive behavior, in ovarian and pancreatic cancer cell lines results in the translocation of CTNND1 to the cytosol, which in turn induces cell migration by activating RAC1 and CDC42." (PMID 27193094, 2016). "Indeed, as shown in pancreatic cancer cells, EGF stimulation leads to tyrosine phosphorylation of Vav1, followed by the activation of a Rac1/Pak1/NF-κB signaling pathway resulting in an increase in cyclin D1 which leads to enhanced pancreatic tumor cell proliferation." (PMID 26353933, 2015). "In addition, this high level of Rac1 activity in the pancreatic cancer cells was unaffected by IR." (PMID 25344910, 2014). "For example, TIPE2 suppresses tumor growth by directly binding to RAC1, whereas TIPE3 promotes pancreatic cancer progression in a RAC1-dependent manner." (PMID 40904408, 2025).
pancreatic cancer (continued). "Mechanistic insights link its activity to Rac1 stimulation, Rho attenuation, and PIK3CD amplification, with further implications in tumor–stroma interplay impacting pancreatic cancer resilience and expansion." (PMID 39624211, 2024). "Active RAC1 can disrupt the interaction between IQGAP1, E-cadherin and β-catenin and reduce cell–cell adhesion in pancreatic cancer cells." (PMID 34439095, 2021). "PAK4, a dual Cdc42/Rac1 effector, is overexpressed in pancreatic CSCs and functions as an upstream activator of STAT3, which is required for pancreatic cancer stemness." (PMID 32915198, 2020). "TGF-β1 stimulates MMP-2 expression through the activation of the Rac1/ROS/NFκB pathway and thus increases invasiveness of SW1990 human pancreatic cancer cells." (PMID 31980722, 2020). "S-nitrosylated proteins in pancreatic cancer pathway identified in this study also include Rac1, Rac2, CDC42, STAT1, and RB, which are all important regulators of pancreatic cancer cells." (PMID 31801946, 2019). "In this model, the pancreas-specific ablation of Rac1 abrogates the development of ADM, delays the formation of PanIN lesions, blocks progression to pancreatic cancer and increases survival." (PMID 28499439, 2017). "CTHRC1 promoted tumor cell migration and invasion by activating Wnt/PCP signaling supported by activating Rac1 in pancreatic cancer, activating RhoA in HCC and activating both Rac1 and RhoA in GIST cells." (PMID 29285247, 2017). "In this study, we demonstrate SET isoform 2 as the predominantly overexpressed form of SET in pancreatic cancer and that it triggers N-cadherin expression for acquisition of EMT characteristics possibly through the Rac-1/JNK/c-jun pathway." (PMID 28978088, 2017). "Supportive evidence came from examining the pancreatic cancer cell lines (PANC-1 and MIA PaCa-2) with abundant expression of SET isoform 2 which correlated with high Rac1 expression at the cell surface." (PMID 28978088, 2017). "Panc-1 and MIA PaCa-2 pancreatic cancer cell lines were treated with ATM for 48hrs and then assayed for Rac1 activity." (PMID 25915428, 2015). "To verify the effect of Rac1 inhibition on cell survival following IR, we transduced CD18/HPAF pancreatic cancer cells and HPNE normal cells with Ad.N17Rac1 or Ad.Control viruses and exposed the cells to IR." (PMID 25344910, 2014). "To examine the role of Rac1 in the cellular response to IR, we analyzed Rac1 protein expression in HPNE and pancreatic cancer cells." (PMID 25344910, 2014). "Recent studies in pancreatic cancer and lung cancer cells that express Vav1 clearly showed that Vav1 functions as a GEF for Rac1 GTPase following EGF stimulation." (PMID 25313137, 2014). "Consistently, Rac1 activity assay demonstrated an association between Rac1 protein level and Rac1 activity in these cells, showing that much higher Rac1 activities were detected in AsPC-1, CD18/HPAF and Capan-1 pancreatic cancer cells compared to HPNE cells." (PMID 25344910, 2014). "Activation of Rac1 in Caco-H2 cells is in agreement with previous studies that correlate Rac1 with EMT and the inhibition of E-cadherin in mammary epithelial and pancreatic carcinoma cells respectively." (PMID 21943101, 2011). "Rac1 mRNA was depleted in Panc1 pancreatic cancer cells and in SU86.86 pancreatic cancer cells by two synthetic duplex RNAi’s to different regions of the Rac1 mRNA." (PMID 24281169, 2010). "In pancreatic cancer, TIPE3 promotes tumor progression by upregulating RAC1." (PMID 40280943, 2025). "Interestingly, studies of breast and pancreatic cancers revealed different effects of RAC1 and RAC1B on transforming growth factor (TGF)-β1-induced cell migration, where RAC1 promoted and RAC1B inhibited TGF-β1-induced cell motility." (PMID 37059183, 2023).
pancreatic cancer (continued). "Previous studies showed p-ezrin directly promotes cell mobility and migration in cancer cell lines through the activation of different signaling pathways, including Rac1, CD44 and Cdc42, while in pancreatic cancer ezrin activates FAK/Akt to promote proliferation." (PMID 36926194, 2023). "Intriguingly, the active deformation of cancer cells, such as murine pancreatic cancer cells and human gastric cancer cells, exhibit no periodic patterns during migration, suggesting the continuous elevation of Rac1 activation." (PMID 33747247, 2021). "The high level of CTHRC1 is connected with the progression and metastasis of pancreatic cancers through the activation of several key signaling molecules, including the steroid receptor coactivator (Src), FAK, paxillin, MEK, ERK, and Ras-related C3 botulinum toxin substrate 1 (Rac1)." (PMID 32848510, 2020). "Likewise, the RAC1-specific GEF TIAM1 plays an important role in proliferation and invasion of pancreatic cancer cells." (PMID 28499439, 2017). "Inhibition of Rac1 activity therefore has a greater negative effect on pancreatic cancer cell survival over HPNE normal pancreatic cells." (PMID 28410221, 2017). "To determine protein levels of the mRNAs modulated by DHA via microRNAs, we next examined Cdk4, Cdk6, VEGF, IKKα, MEK1, E2F3, Rac1, E2F1, and CDC42 protein levels, which affect growth, inhibit angiogenesis, and promote apoptosis in DHA-treated and vehicle-treated pancreatic cancer cells." (PMID 27613829, 2016). "Surprisingly, we found that four crucial microRNAs (miR-34a-5p, miR-195-5p, miR-30c-5p, and miR-130b-3p) regulated the expression of many mRNAs (Cdk4, Cdk6, VEGF, IKKα, MEK1, E2F3, Rac1, E2F1, ERK1, and CDC42) and their proteins, and thus were crucial to the anti-pancreatic cancer effects of DHA." (PMID 27613829, 2016). "In summary, the results of these studies indicate that the inhibition of Rac1, either by NSC23766 or expression of N17Rac1, augments the sensitivity of CD18/HPAF pancreatic cancer cells to IR, whereas it has little effect on the sensitivity of HPNE normal cells to IR." (PMID 25344910, 2014). "In summary, results of these studies indicate that the inhibition of Rac1 using either pharmacological inhibitor or dominant negative mutant promotes apoptosis induction after IR in pancreatic cancer cells." (PMID 25344910, 2014). "Inhibiting Rac1 activity (Rac1 mutant construct) inhibits the growth of mutant K-RAS human pancreatic cancer cells but not pancreatic cancer cells with wild-type K-RAS in a superoxide-dependent manner." (PMID 23434665, 2013). "Both compounds had EC50 in the low micromolar range for inhibition of PAK1 binding to Rac1 present in the EGF-stimulated CD18/HPAF cells, suggesting that compounds #1 and #6 will be effective in the inhibition of sustained hyper-activation of Rac1 seen in pancreatic cancer cells." (PMID 28410221, 2017). "These compounds do not share the core structure of the known Rac1 inhibitors and could serve as additional lead compounds to target pancreatic cancers with high Rac1 activity." (PMID 28410221, 2017). "Moreover, ARHGAP31 is not previously associated with pancreatic cancer, but has well-studied roles in actin modulation, since ARHGAP31 is the human orthologue for the mouse protein CdGAP (mCdc42 GTPase-activating protein) and ARHGAP31 inactivates the GTPases CDC42 and RAC1." (PMID 39110005, 2024).
gastric cancer (69 papers, 2009 to 2025). A primary or metastatic malignant neoplasm involving the stomach. "Using yeast two-hybrid screening, they reported key regulatory roles for RhoGDIβ in promoting an interaction between Rac1 and Filamin A and the associated activation of Rac1 in the invasiveness of gastric cancer cells." (PMID 40710299, 2025). "Evidence suggests that hyperactivation and overexpression of Rac1 are associated with gastric cancer in multiple aspects." (PMID 41188920, 2025). "Overexpression of Rac1 in gastric cancer is mechanistically linked to enhanced tumor proliferation and aggressive metastatic spread." (PMID 41188920, 2025). "Rac1 is implicated in hypoxia and oxidative stress in gastric cancer, facilitating the migration of gastric cancer cells." (PMID 41188920, 2025). "RAC1 is overexpressed in different types of tumors, including colorectal and gastric cancers, and is associated with a poor prognosis." (PMID 38378644, 2024). "By employing the H-score, the expression levels of ITGB6 and Rac1 were determined and compared between gastric carcinoma tissues and adjacent normal tissues within the diagnostic cohort." (PMID 38344200, 2024). "Importantly, our study showed that the expression levels of ITGB6 and Rac1 are associated with the unfavorable prognosis of gastric cancer patients." (PMID 38344200, 2024). "Moreover, the increased expression of RhoA and Rac1 among the Rho-GTPase family proteins is associated with gastric cancer progression." (PMID 27333045, 2016). "Together, these studies revealed critical roles for RhoGDIβ in promoting an interaction between Filamin-Rac1-Trio in exerting the invasive ability of gastric cancer cells." (PMID 40710299, 2025). "For example, icariin, a purified extract from the Herba epimedium (a traditional Chinese medicine), adversely impacts the invasion and migration of gastric cancer cells through the Rac1-dependent vasodilator-stimulated phosphoprotein (VASP) pathway." (PMID 41188920, 2025). "Kim and coworkers defined the roles of the RhoGDIβ-Rac1 module in tumor growth progression in gastric cancer." (PMID 40710299, 2025). "Nectin-4, a cell adhesion molecule highly expressed in gastric cancer, activates Rac1 via the PI3K/AKT signaling pathway, enhancing lamellipodia formation, cellular migration, and proliferation." (PMID 41188920, 2025). "This review advances the understanding of Rac1’s role in gastric cancer, provides a theoretical foundation for further studies, and supports the development of precision medicine for this disease." (PMID 41188920, 2025). "Despite the availability of new molecular inhibitors, studies focusing on Rac1 inhibition in gastric cancer are still limited." (PMID 41188920, 2025). "Integrin α5 (ITGA5) activates the FAK/Src/Rac1 pathway, fostering the malignant characteristics of gastric cancer cells and improving adhesion between cells and extracellular matrix proteins." (PMID 41188920, 2025). "The potential of Rac1 as a therapeutic biomarker in gastric cancer and the remaining challenges in this area are also discussed." (PMID 41188920, 2025). "Extensive studies have confirmed the Rac1 oncogenic function, including gastric cancer, colon cancer, breast cancer, lung cancer, prostate cancer, ovarian cancer, and pancreatic cancer." (PMID 41188920, 2025). "The role of RAS-related C3 botulinum toxin substrate 1 (Rac1) is mediation of β-catenin nuclear localization, and its activation promotes the proliferation, invasion, and drug resistance of gastric cancer cells." (PMID 38952556, 2024). "The present study investigate the expression and correlation of ITGB6 and Rac1 proteins in gastric cancer tissues." (PMID 38344200, 2024). "And vice versa, inhibiting the activity of Rac1 results in decreased proliferation, invasion, and metastasis capabilities of gastric cancer cells expressing ITGB6." (PMID 38344200, 2024).
gastric cancer (continued). "The objective of this study is to explore the association and clinical relevance of Rac1 and ITGB6 expression in gastric cancer." (PMID 38344200, 2024). "The correlation of integrin αvβ6 expression and RAC1 expression with clinicopathologic variables in cases of gastric cancer." (PMID 38344200, 2024). "Both the Kaplan-Meier survival analysis and Cox regression model analysis demonstrated that the presence of positive expression of ITGB6 and Rac1 proteins served as independent prognostic factors for gastric cancer." (PMID 38344200, 2024). "To conclude, our study findings indicate that the levels of ITGB6 and Rac1 are heightened in gastric carcinoma and exhibit a correlation, thereby linking them to tumor advancement and unfavorable prognosis among gastric cancer patients." (PMID 38344200, 2024). "Transwell migration and invasion experiments (with Matri-gel) were conducted to explore the effects of si-ITGB6 and Rac1 inhibitor on the migration and invasion ability of gastric cancer cells." (PMID 38344200, 2024). "Immunostaining was conducted to ascertain the expression of ITGB6 and Rac1 in gastric carcinoma specimens in comparison to neighboring normal tissues." (PMID 38344200, 2024). "Taken together, these findings suggested a novel role of ARHGAP15 in promoting gastric cancer metastasis by quenching ROS through inhibiting RAC1 and its potential value for prognosis estimation and targeted therapy." (PMID 36802400, 2023). "Through miR-148b-3p, Rac1 and Cdc42 can be activated, which directly affect the motility of gastric cancer cells, and can serve as a new treatment strategy specific to gastric cancer." (PMID 37274025, 2023). "In conclusion, we demonstrated ARHGAP15 promoted metastatic colonization by enhancing the antioxidant capacity of gastric cancer cells in a RAC1 dependent way." (PMID 36802400, 2023). "In this study, the impact of silencing Rac1 and Prex1 on transforming growth factor-beta 1-induced epithelial–mesenchymal transition and apoptosis of human gastric cancer cells MGC-803 and MKN45 was investigated." (PMID 37434402, 2023). "Our experiments using Cdc42-, Rac1-, and Rho-blocking agents revealed that the Cdc42 GTPase inhibitor resulted in a dose-dependent decrease in cell attachment of all four gastric cancer cell lines." (PMID 35723363, 2022). "Conclusively, RhoGDI2 increases Rac1 activity by recruiting Rac1 to Filamin A and enhancing the interaction between Rac1 and Trio, which is critical for invasive ability of gastric cancer cells." (PMID 35008419, 2022). "Depletion of Filamin A expression markedly reduced Rac1 activity in RhoGDI2-expressing gastric cancer cells." (PMID 35008419, 2022). "We previously showed that RhoGDI2 positively regulates Rac1 activity and Rac1 activation is critical for RhoGDI2-induced gastric cancer cell invasion." (PMID 35008419, 2022). "In this field of research, miRNA-150 was found to repress both Wnt and Hedgehog pathways in gastric cancer, while miR-375 regulated the Hedgehog pathway via Ras-related C3 botulinum toxin substrate 1 (RAC1)." (PMID 35873564, 2022). "In this study, we aimed to uncover the molecular mechanism by which RhoGDI2 activates Rac1 activity and promotes metastatic characteristics of gastric cancer cells." (PMID 35008419, 2022). "Following these studies, we investigated the activation status of Rho GTPases in RhoGDI2-expressing and -depleted cells, and discovered that RhoGDI2 activates Rac1 exclusively in gastric cancer cells." (PMID 35008419, 2022). "Rho GDP dissociation inhibitor 2 (RhoGDI2), a regulator of Rho family GTPase, has been known to promote tumor growth and malignant progression by activating Rac1 in gastric cancer." (PMID 35008419, 2022). "In conclusion, our study reveals a novel mechanism for RhoGDI2-induced Rac1 activation in gastric cancer cells." (PMID 35008419, 2022). "In gastric cancer tissues, the expression of RAC1 was increased, which was significantly related to TNM stage." (PMID 35280778, 2022).